SOD1 (superoxide dismutase 1)
Diseases named in the same sentence as SOD1 in open-access papers (continued):
Sharing a sentence is not in itself a finding about the gene and the disease.
neurological diseases (42 papers, 2010 to 2025). "The large effect size and strong statistical significance observed between ALS patients and both healthy and neurological disease controls support the diagnostic potential of trimeric SOD1." (PMID 40709254, 2025). "Mutation in SOD1 compromises its functions, resulting in hereditary and neurological diseases including ALS." (PMID 36672132, 2023). "Other lethal neurological diseases are also caused by accumulation of denatured toxic proteins including SOD1 G93A in ALS and Huntingtin in HC." (PMID 34252884, 2021). "In dogs over 8 years of age, homozygosity for the SOD1:c.118A allele was strongly associated with those affected with pelvic limb ataxia, compared to those referred with non-neurological disease." (PMID 26401327, 2014). "Only three of our seven probands (43%) had a family history of neurological disease, which is significantly less than for C9orf72 and SOD1 mutations and suggests that TIA1 mutations may be variably penetrant." (PMID 29216908, 2017). "ASOs have emerged as a promising RNA‐targeting strategy for neurological diseases, represented by the recent US FDA approval of tofersen, an ASO designed to reduce SOD1 mRNA in ALS patients carrying SOD1 mutations." (PMID 41355735, 2025). "To better understand the specificity of our SOD1 RT-QuIC assay, we examined neurological tissue-matched specimens from patients clinically diagnosed with other neurological diseases (#s 8–12)." (PMID 38884646, 2024). "Anomalies in SOD1 can also result in neurological diseases, ophthalmic diseases, organismal injuries and abnormalities, and psychological disorders." (PMID 36672132, 2023). "Such biotinylation-dependent 32-kDa species of SOD1 also existed in some of normal healthy controls and patients with other neurological diseases, which was, however, reported to be statistically insignificant." (PMID 22830015, 2012). "Stathmin overexpression and Golgi fragmentation seem to be early events in the neurodegenerative cascade characteristic of ALS and other neurological diseases, and has been confirmed by transcriptional analysis in pre-symptomatic G93A SOD1 mice." (PMID 20352044, 2010). "ALS is a serious neurological disease in which the cortex, brainstem, and spinal motor neurons are affected by prion-like misfolded proteins, e.g., superoxide dismutase-1 (SOD1) and TDP-43, resulting in neurodegeneration and is disease marked by protein dysfunction without RNA or DNA components." (PMID 31636538, 2019). "SOD1 TG/IL-6(-/-) mice (n = 17) were compared with SOD1 TG/IL-6(+/-) mice (n = 18), SOD1 TG/IL-6(+/+) mice (n = 11), WT mice (n = 15), IL-6(+/-) mice (n = 5) and IL-6(-/-) mice (n = 8), with respect to neurological disease severity score, body weight and the survival." (PMID 27070121, 2016). "Furthermore, salubrinal shows neuroprotective effects in vitro and in vivo against neurotoxic substances considered to be responsible for neurological disorders, such as β-amyloid, α-synuclein, mutant huntingtin protein, superoxide dismutase 1 mutant, ceramide, and kainic acid." (PMID 26193263, 2015). "Importantly, these antibodies detected small round inclusions in spinal motor neurons of all the 29 sporadic and 8 familial ALS cases lacking mutations in sod1 gene; the abundance of such inclusions was much smaller in controls without neurological diseases." (PMID 22830015, 2012). "In addition, we also identified decreased levels of BDNF, in SOD1-ALS MNs, which is a key growth factor required for the cell growth/neuronal survival in the brain, whereas reduced expression has been associated with neuronal dysfunction and death in several neurological disorders including ALS." (PMID 39588282, 2024). "On the other hand, we identified 11 and 26 common transcriptional regulators between FUS- and SOD1-ALS in our datasets and GSE106382 dataset, suggesting their involvement in many neurological diseases including ALS." (PMID 32967368, 2020).
neurological diseases (continued). "Our findings suggest that the microbiota play a protective role in the SOD1 model of ALS by restraining MGnD microglia, which is opposite to other neurologic disease models, and sheds new light on the importance of disease-specific interactions between microbiota and microglia." (PMID 35272713, 2022). "Arguably, the slow progression of neurologic disease, spanning for clinical onset at 5–6 months of age to progression over another 10–12 months, and the specific clinical features of the disease in G59S-DCTN1 tg mice better mirror human ALS than the more commonly used tg SOD1 mouse models." (PMID 41463293, 2025). "The observation that SOD1 mice have worse disease progression with antibiotics is unique compared to other models of neurologic disease, but whether the gut microbiota affects microglia in SOD1 mice is not known." (PMID 35272713, 2022).
metabolic disorders (30 papers, 2015 to 2025). "As a gene encoding an important antioxidant enzyme, SOD1 may have its SNPs gender-differentially correlated with metabolic diseases." (PMID 32559230, 2020). "Previous studies showed that long-term metabolic disorder affected the function of mitochondria, and decreased the activity of enzymatic antioxidant, such as SOD1 and GPX1." (PMID 25747866, 2015). "The novel perspective of our newly elucidated, unorthodox roles of SOD1 may offer alternative mechanisms to explain paradoxical phenotypes of metabolic disorders." (PMID 36834640, 2023).
nephropathy (28 papers, 2012 to 2025). A nonspecific term referring to disease or damage of the kidneys. "The results showed that gallic acid exhibits a significantly strong interaction with genes such as CASPs, ILs, AGTR1, ACE2, SOD1, etc., while caffeic acid and ferulic acid showed comparatively low interaction with the genes involved in the pathophysiology of the kidney disease." (PMID 36672676, 2023). "Network pharmacology analysis showed significant biological interaction of NEERI KFT metabolites, especially polyphenols, which regulate the expression of several genomes (CASPs, ILs, AGTR1, AKT, ACE2, SOD1, etc.)that are involved in the pathophysiology of kidney disease." (PMID 36672676, 2023). "Although the SOD1 isoform represents up to 80% of the total SOD activity in the mammalian kidney, SOD2 appears to be more important in the pathogenesis of kidney disease." (PMID 31885800, 2019).
bacterial infection (23 papers, 2015 to 2025). "It has been shown that ABPs improved the intestinal flora and showed resistance to bacterial infections, and also significantly increased the expression of intestinal antioxidant genes SOD1 and CAT to enhance the antioxidant capacity of broiler chickens." (PMID 40351762, 2025).
inflammation (18 papers, 2015 to 2025). Aberrant reaction of the microcirculation characterized by movement of fluid and leukocytes from the blood into extravascular tissues. "Pulmonary inflammation was significantly affected by acute inflammation, as demonstrated by immune cell infiltration and NF-kB target gene (IL-6, CRP, COX-2, SOD1) upregulation." (PMID 34086835, 2021). "Treating aged WT or adult Sod1−/− mice with necrostatin-1s, a RIPK1 inhibitor, reduces liver inflammation and MASH pathology, underscoring the necroptosis pathway’s role in age-related liver inflammation and MASH." (PMID 39930289, 2025).
peripheral neuropathy (14 papers, 2013 to 2025). A disorder affecting the peripheral nervous system. "As dismutase activity is only 1% of WT animals in the SOD1 D83G homozygotes, this peripheral neuropathy may be due to a loss of dismutase activity, potentially leading to increased vulnerability of peripheral motor axons to oxidative stress." (PMID 25468678, 2015). "This distribution supports the diagnosis of length-dependent peripheral neuropathy and is consistent with the clinical presentation of SOD1-IPN." (PMID 39932579, 2025). "A single-copy ALS SOD1 knock-in mouse model shows peripheral neuropathy, reminiscent of SOD1 null mice." (PMID 30296255, 2018). "Further support of the importance of the IMS-fraction of SOD1 arise from the finding that the peripheral neuropathy of the SOD1 knockout mice can be rescue by expression of wild-type SOD1 targeted specifically to the IMS." (PMID 24955214, 2014). "Sod1−/− mice exhibit a peripheral neuropathy phenotype with normal sensory nerve function and deficits in motor nerve function." (PMID 23844146, 2013). "There was clearly an age-related effect in Sod1−/− mice as myelin thickness was significantly reduced by 20 months of age which affirms that oxidative stress is indeed one of the critical determinants for demyelination in peripheral neuropathies." (PMID 23750273, 2013). "In SOD1-ALS, LOF can play a role in disease pathogenesis, as Sod1 KO mice develop a severe peripheral neuropathy, leading to denervation and SOD1-ALS patients generally have diminished SOD1 dismutase activity." (PMID 30626575, 2019). "Although axon degeneration is rescued by SARM1 deletion in some models (e.g. chemotherapy-induced peripheral neuropathy; TDP43-linked ALS), it is not in others (SOD1 mouse model of ALS; and optic nerve crush)." (PMID 36778383, 2024).
retinopathy (9 papers, 2014 to 2024). "Superoxide dismutase (SOD) genotype reconstruction showed that SOD1 (GG) and SOD2 (GT) alleles decrease the risk of retinopathy of prematurity in preterm babies." (PMID 24847438, 2014).
adenocarcinoma (8 papers, 2009 to 2024). A common cancer characterized by the presence of malignant glandular cells. "SOD1 had markedly higher mRNA levels compared with SOD2 or SOD3, the latter being significantly downregulated in adenocarcinoma tissues." (PMID 29478325, 2019).
heart disease (7 papers, 2013 to 2024). "Overexpression of the SOD1 gene has been shown to be beneficial in various animal models of cardiac diseases." (PMID 27932994, 2016). "The fact that SOD1 levels were found to be higher among male, hypertensive, and heart disease patients could be ascribed to high oxidative stress in these patients." (PMID 24363822, 2013). "The SOD1 levels were found to be higher among hypertensive patients (P = 0.015), those with heart disease (P = 0.002) and male AMD patients (P = 0.035), as compared to nonhypertensive patients or those without heart disease and female AMD patients, respectively." (PMID 24363822, 2013).
brain diseases (4 papers, 2020 to 2023). "In contrast to its protective antioxidant function, mutations in SOD1 result in brain diseases." (PMID 36672132, 2023). "Therefore, these promising results of SOD1-POx conjugates indicate the therapeutic potential of POxylated SOD1 in the treatments of superoxide-related brain diseases." (PMID 32325941, 2020).
genetic diseases (4 papers, 2018 to 2025). "Most fALS cases involve autosomal genetic diseases, such as superoxide dismutase-1 (SOD1) and nerve microfilament defects." (PMID 32792920, 2020).
movement disorder (4 papers, 2017 to 2024). Neurological conditions resulting in abnormal voluntary or involuntary movement, which may impact the speed, fluency, quality and ease of movement. "Deficiency of SOD1 leads to early-onset movement disorders with full penetrance, while mutations that lead to SOD1 aggregation cause motor neuron death with variable and age-dependent penetrance." (PMID 33677640, 2021). "The D. melanogaster model's widespread downregulation of SOD1 expression accelerates age-dependent movement disorders and shortens the lifespan of D. melanogaster." (PMID 38500677, 2024). "It seems that the progression of Purkinje cell phenotypic alterations and probably degeneration is faster in a subpopulation of the wt SOD1 Tg mice and this leads to appearance of movement disorders and unsteady gait behavior in mice." (PMID 28424594, 2017). "Moreover, the hSOD1WTtransgenic D. melanogaster model extended the longevity of the SOD1 deletion mutant and normal D. melanogaster but did not prevent age-dependent movement disorders." (PMID 38500677, 2024).
neuromuscular disease (4 papers, 2014 to 2024). "Furthermore, progression of neuromuscular disease in ALS model zebrafish was accelerated when this homologue of GDF6 was mutated: older zebrafish expressing mutant SOD1 exhibit ALS-like symptoms, but young fish only exhibited significant ALS-like neuromuscular deficits when on a gdf6a−/− background." (PMID 24586579, 2014).
autosomal dominant disease (3 papers, 2013 to 2022). Autosomal dominant form of disease. "Around 10–20% of ALS is an inherited autosomal-dominant disease and of these familial cases, about 10% are due to mutations in the superoxide dismutase 1 (SOD1) gene." (PMID 24035135, 2013).
central nervous system disorder (3 papers, 2018 to 2024). A disease involving the central nervous system. "A series of studies and therapeutic developments related to SOD1 mutations have advanced the understanding of ALS pathophysiology and significantly contributed to treatment strategies for central nervous system disorders." (PMID 39457466, 2024). "It seems that transfected BMSCs capable of secreting SOD1 are a suitable source of combined therapy for the central nervous system disorders due to the neuronal support provided by neurotrophin secretion from such cells as well as detoxifying and neutralizing superoxide anions by SOD1 secretion." (PMID 30140407, 2018).
bone disorder (1 paper, 2023). "Both SOD1 and SOD2 have been suggested as therapeutic targets for bone disorders." (PMID 36185749, 2023).
neurodevelopmental disorder (1 paper, 2021). A behavioral and cognitive disorder with onset during the developmental period that involves impaired or aberrant development of intellectual, motor, or social functions. "Surprisingly, genes associated with neurodevelopmental disorders were enriched in genes upregulated in the SOD1 V1 ipINs." (PMID 34767750, 2021).
neurogenetic disease (1 paper, 2024). "Among the four, PSEN1 and PSEN2 are known AD-related genes, reported in AlzGene, while C9orf72 and SOD1 are known to be relevant to neurogenetic disease and possess AD-relevant literature support in GeneCards." (PMID 38627848, 2024).
SOD1 also shares sentences with these, for which no sentence is quoted: ulcer (59 papers); hyperlipidemia (48); Anxiety (41); Hypercholesterolemia (31); acute kidney injury (28); vitiligo (19); hyperuricemia (18); liver (17); alcohol (15); chronic periodontitis (14); periodontal disease (14); diabetic retinopathy (13); Myocardial fibrosis (13); rheumatoid arthritis (13); liver cirrhosis (12); nonalcoholic fatty liver disease (10); pancreatitis (10); brain injury (9); brucellosis (9); chronic heart failure (9); hyperthyroidism (9); malnutrition (9); duodenal ulcer (8); immune disorders (8); lung disease (8); allergic asthma (7); bipolar disorder (7); coccidiosis (7); endometritis (7); kidney (7).
A further 546 diseases each share a sentence with SOD1 in 7 papers or fewer.